NLRP3 (NLR family pyrin domain containing 3)
Diseases named in the same sentence as NLRP3 in open-access papers (continued):
Sharing a sentence is not in itself a finding about the gene and the disease.
COVID-19 (401 papers, 2020 to 2026). A disease caused by infection with severe acute respiratory syndrome coronavirus 2. "Due to this crucial role in triggering inflammatory response to infection, the NLRP3 inflammasome appears to be a potential drug target in the treatment of coronavirus disease 2019 (COVID-19), caused by SARS-CoV-2." (PMID 32574259, 2020). "The COVID-19-related long-standing effect or Post-Acute Sequelae of COVID-19 (PASC) is often associated with NLRP3 inflammasome activation in pulmonary inflammation elicited by SARS-CoV-2 spike proteins." (PMID 40724579, 2025). "In the context of acute respiratory distress syndrome (ARDS) caused by COVID-19, metformin has been reported to inhibit NLRP3 inflammasome activation and IL-1β production in macrophages." (PMID 40405092, 2025). "During SARS-CoV-2 infection, activation of the NOD-like receptor family pyrin domain-containing 3 (NLRP3) inflammasome pathway is thought to contribute to the release of bioactive IL-1β and IL-18, cytokines associated with severe COVID-19." (PMID 40016339, 2025). "Excessive or chronic stimulation of NLRP3 inflammasome has been implicated in inflammation-associated COVID-19 pathology and long-term lung inflammation-associated PASC." (PMID 40724579, 2025). "For instance, ORF3a activates NLRP3, triggering cytokine storms linked to tissue damage and organ failure in severe COVID-19 cases." (PMID 38251382, 2024). "A cause of the complications of COVID-19 is the cytokine storm generated by the abnormally activated NLRP3 inflammasome." (PMID 39070405, 2024). "A well-established fact is that the cause of COVID-19 complications is the hyperactivation of the NLRP3 inflammasome in leukocytes, which is inhibited by high concentrations of colchicine." (PMID 39070405, 2024). "For depression, as an increased risk after COVID-19 vaccination, the results were shown for the deep interaction of spike protein-related factors such as NLRP3 inflammasome." (PMID 38834668, 2024). "Treatment with MSCs has the potential to reduce cytokine production associated with COVID-19-induced acute respiratory distress syndrome by targeting the molecular cascade of the NF-κB/NLRP3 pathway." (PMID 38675960, 2024). "Similar to COVID-19-associated myocarditis, autoimmunity-associated myocarditis results in upregulated activation of the NLRP3 and NF-κB pathways in addition to an increase in IL-1β level." (PMID 38650023, 2024). "The absence of notable disparities in inflammatory cytokines, chemokines and the NLRP3 risk variant suggests a more nuanced interaction between sex and immune response in COVID-19." (PMID 38919940, 2024). "It has the unique property of accumulating in leukocytes, which is the primary cause of the abnormal activation of the NLRP3 inflammasome in COVID-19." (PMID 39070405, 2024). "Freeman and Swartz showed that SARS-CoV-2 infection is linked to NLRP3 activation, which is inhibited by double corticosteroid-interferon administration, which improves clinical outcomes in patients with severe COVID-19." (PMID 37383608, 2023). "Myocarditis is regarded as a rare complication of COVID-19, and the pathogenic process of COVID-19-related myocarditis also indicates the involvement of the NLRP3 inflammasome." (PMID 37256114, 2023). "As we observed that the expression levels of NLRP3/IL-1β were downregulated in the innate immune cells from COVID-19 patients, we wanted to further explore the protein encoded by the SARS-CoV-2 genome involved in the downregulated NLRP3 inflammasome pathway." (PMID 38004809, 2023). "Being both P2X7R and NLRP3 tightly associated to the release of inflammatory cytokines, a reasonable anticipation is that their blood levels in COVID-19 should parallel that of the cytokines typically overexpressed in this disease, e.g., IL-6 and IL-10." (PMID 37215142, 2023). "NLRP3 inflammasome gene variants were correlated with critical COVID-19 in the Brazilian population." (PMID 37251383, 2023).
COVID-19 (continued). "This association makes sense, considering that a significant cause of COVID-19 pathogenesis and subsequent severity is the cytokine storm associated with NLRP3 overactivation." (PMID 36899820, 2023). "The activation and dysregulation of the NACHT, leucine-rich repeat, and pyrin domain-containing protein 3 (NLRP3) inflammasome in circulating neutrophils are associated with worsening of COVID-19." (PMID 37113134, 2023). "As Colc reduces the inflammasome of NLRP3, it has been suggested for application in infections caused by COVID-19." (PMID 37513411, 2023). "Other genes commonly associated with COVID-19 immune responses (e.g., Stat1, Myd88, Il1b Nlrp3, Cdkn1a, and Casp1) were also upregulated in responder brains." (PMID 36739463, 2023). "The use of Colc in COVID-19 relies on the NLRP3 inflammasome activation caused by viroporin E, which is a component of COVID-19 and has an inflammatory response." (PMID 37513411, 2023). "An early indication of a role for NLRP3 in COVID-19 came from an association between LDH levels and several disease severity scores." (PMID 36661317, 2023). "There was further downregulation of the NLRP3-IL1β pathways, which have also been implicated in the pathogenesis of COVID-19." (PMID 36851206, 2023). "Respiratory inflammasome activation and dysregulation of the NACHT, leucine-rich repeat, and pyrin domain-containing protein 3 (NLRP3) inflammasome in circulating neutrophils are associated with worsening of COVID-19." (PMID 37113134, 2023). "The NLRP3 inflammasome was constitutively activated in COVID-19 patients with underlying liver diseases such as cirrhosis, acute live failure and non-alcoholic fatty liver disease (NAFLD)." (PMID 37251383, 2023). "NLRP3 inflammasome activation and NETs have been associated with a wide range of pathology, including thrombosis, ischemia reperfusion injury, severe COVID-19, acute GVHD, and solid organ graft rejection." (PMID 37744381, 2023). "COVID-19 is characterised by a cytokine storm and the Pyrin domain containing 3 (NLRP3) inflammasome has been implicated." (PMID 35720378, 2022). "The NLRP3 inflammasome, which functions as an important part of the innate immune system, has been shown to be associated with COVID-19 severity in patients." (PMID 34979342, 2022). "Many articles have reported that the SARS-CoV-2 infection can stimulate NLRP3-mediated COVID-19 inflammation, which has been associated with severity in long-COVID patients." (PMID 36698809, 2022). "In this study, we investigated how polymorphisms in GSTO1-1, as an enzyme involved in activation of the NLRP3 inflammasome, modify risk of COVID-19." (PMID 35330457, 2022). "Since Nlrp3 deficiency alleviated COVID-19 like pathology in lungs, we were stimulated to study the underlying mechanism." (PMID 34979342, 2022). "What is still unclear is the exact molecular mechanisms by which the NLRP3 rs1539019 polymorphism plays a protective effect in the outcome of COVID-19." (PMID 36105941, 2022). "Using whole blood transcriptomics analysis, increased NLRP3 inflammasome, monocytes and LDGs were found in the lungs of COVID-19 patients, and neutrophil activation-associated signatures correlated to disease severity." (PMID 35720378, 2022). "It has been confirmed that NLRP3 inflammasome activation in response to SARS-CoV-2 replication is closely associated with COVID-19 related cytokine storm in patients with severe disease." (PMID 34979342, 2022). "With COVID-19 patients known to manifest neurological symptoms and NLRP3 known to be implicated in neurological diseases like Alzheimer’s —blocking IL-1 can conceivably be more efficacious than IL-6 in managing COVID-19." (PMID 35431536, 2022). "On one side our COVID-19 cohort presented elevated expression of NLRP3 in monocytes which was associated to eATP concentration." (PMID 35173744, 2022).
COVID-19 (continued). "It is important to underline that prolonged activation of NLRP3 leads to an increase in the levels of IL-1β and IL-18 which are associated with more severe forms of COVID-19." (PMID 35566589, 2022). "So far, several studies have reported hyperactivation of the NLRP3 inflammasome in COVID-19, as well as its relation to pathologies associated with severe COVID-19 such as acute respiratory distress syndrome (ARDS) and acute lung injury (ALI)." (PMID 35330457, 2022). "A recent study showed that two NLRP3 variants play an important role in severe and critical COVID-19." (PMID 36105941, 2022). "All sections from lungs of COVID-19 ARDS, non-COVID-19 ARDS subjects stained positively for the NLRP3 inflammasome associated markers that were assessed by fluorescence imaging." (PMID 35144622, 2022). "The critical role of NLRP3 inflammasome in ALI/ARDS of different causes including COVID-19 makes it worthwhile to investigate the detailed mechanisms and targeting therapies." (PMID 36618363, 2022). "As the condition “long COVID-19” is also associated with a prolonged inflammatory state, an extended NLRP3 treatment period should also be considered." (PMID 35626754, 2022). "In previous studies, the JAKs/STAT3 for signal transduction can activate pro-inflammatory gene expressions and facilitate the NLRP3 inflammasome to secrete IL-1β and IL-18 during the pathogenesis of COVID-19-associated neurodegenerative diseases." (PMID 36698809, 2022). "In the present study, we classified patients at presentation according to the WHO severity classification and identified CARD8 and NLRP3 polymorphisms associated with protection against COVID-19 severity." (PMID 36105941, 2022). "Conclusions and Relevance: Cholesterol can indirectly increase the susceptibility of patients to SARS-CoV-2 and increase the risk of death from COVID-19, which are mediated by NLRP3 and atherosclerotic plaques, respectively." (PMID 34522180, 2021). "Owing to its role in the exacerbation of symptoms and tissue damage during viral infection, NLRP3 represents an attractive target for reducing the severity of COVID-19-associated neurological damage." (PMID 34944639, 2021). "SARS-CoV-2 infection activates NLRP3 inflammasome in COVID-19 patients, and this activation is associated with the severity of COVID-19." (PMID 34440201, 2021). "Activation of NLRP3 inflammasome is also related with COVID-19 severity and associated complications like ALI and ARDS." (PMID 34568081, 2021). "Network plot analysis showed that NLRP3 was associated with the presence of headache in COVID-19 and correlated with both the duration of headache and the duration of hospital stay in our study." (PMID 34384355, 2021). "Of note, activation of nod-like receptor pyrin 3 (NLRP3) inflammasome is linked to over-activation of NF-κB signaling-induced inflammatory reactions in COVID-19." (PMID 34568081, 2021). "In peripheral blood mononuclear cells, active NLRP3 inflammasome was observed and was associated with disease severity in COVID-19 patients." (PMID 34944639, 2021). "Treatments targeting NLRP3 inflammasome have been suggested to mitigate COVID-19-associated inflammation and complications." (PMID 34439920, 2021). "NLRP3 is activated in patients with COVID-19 and both IL-18 and active caspase 1 can be associated with distinct levels of the disease." (PMID 34471404, 2021). "COVID-19 seems to be associated with a massive inflammatory response that appears to occur via stimulation of the NLRP3 inflammasome." (PMID 33562758, 2021). "Most relevant to this review, the viroporins of SARS-CoV, such as protein E, have been shown to activate the NLRP3 inflammasome and are associated with COVID-19 severity in patients." (PMID 34112082, 2021). "Many studies have revealed various regulators of NOD-, LRR-, and pyrin domain-containing protein 3 (NLRP3) inflammasome activation, while it has been recently shown that NLRP3 is implicated in COVID-19 pathogenesis." (PMID 34835501, 2021).
COVID-19 (continued). "The main cause of inflammation in COVID-19 is the so-called “cytokine storm”, underlining the importance of the NLRP3 inflammasome." (PMID 34112082, 2021). "Other possible associations remain 28, but NLRP3 is a good explanation for cholesterol's role in COVID-19 susceptibility." (PMID 34522180, 2021). "During COVID-19, the chronic inflammatory state promotes the cytokine shock, characteristic of severe forms, caused in particular by excessive activation of the NLRP3 inflammasome." (PMID 33668493, 2021). "Other than COVID-19, there are also NLRP3 inflammasome-associated diseases in which sex elements play a central role." (PMID 34150848, 2021). "Nevertheless, cytokine storm is the main cause of inflammation in COVID-19 highlighting an important role of NLRP3 inflammasome." (PMID 32574259, 2020). "With regard to the exacerbated inflammation probably caused by aberrant activation of NLRP3 inflammasome in COVID-19, potential targets are being explored including host signaling proteins and effector molecules that lead cytokine storm." (PMID 33193349, 2020). "The NLRP3 inflammasome is activated in response to severe acute respiratory syndrome coronavirus 2 (SARS-CoV-2) infection, and its activation status is positively correlated with disease severity and mortality in patients." (PMID 40508226, 2025). "Interestingly, intense Casp1p20 expression was also detected in abundance (>90%) at sites of vascular injury and vessel thrombosis, indicating a spatial association between NLRP3-inflammasome activation and COVID-19-associated vasculopathy." (PMID 39882243, 2024). "It was probably not a coincidence that the inflammasome activation triggered by mild COVID-19 resulted in such a devastating outcome in this patient, considering the patient’s background of chronic cholestasis and potentially low-grade NLRP3 activity in association with PBC." (PMID 39459978, 2024). "All these recently published data support our thesis about the life-saving effect of colchicine not only in COVID-19 but also in other viral infections, such as seasonal influenza-associated with hyperactivation of the NLRP3 inflammasome and its subsequent cytokine storm." (PMID 39070405, 2024). "NLRP3 inflammatory bodies function as sensors for cellular stress and danger signals, with disruptions in their regulation implicated in various inflammatory diseases, including those linked to severe viral infections like COVID-19." (PMID 38399989, 2024). "Thus, it is associated with the chronic stages of COVID-19 in humans and preclinical mouse models since the activation of NLRP3-dependent inflammasomes produces proinflammatory substances." (PMID 38391754, 2024). "Our results support the hypothesis that NLRP3-Inflammasome could be implicated in the process of fibrotic evolution of COVID-19-associated ARDS." (PMID 37685844, 2023). "Besides, activation of NLRP3 inflammasome is associated with more expression of NF-κB, which increases inflammatory disorders via the release of pro-inflammatory cytokines in COVID-19." (PMID 37796433, 2023). "The reduced neutrophilic responsiveness towards common NLRP3 stimuli could predispose severe COVID-19 patients to secondary pathogen infections." (PMID 37251383, 2023). "Proinflammatory cytokines and acute-phase reactants such as IL-1β and IL-18 caused by COVID-19 around NLRP3 activation may directly or indirectly cause inflammation and pancreatic β cell damage, resulting in severe insulin resistance and hyperglycemia." (PMID 37868953, 2023). "This study demonstrated the significant participation of the NLRP3 inflammasome in inducing the inflammatory cytokine storm, the main pathogenic mechanism of COVID-19-related myocarditis, and provided ideas for the treatment of COVID-19-related myocarditis." (PMID 37256114, 2023).
COVID-19 (continued). "Altogether, our data demonstrates that SARS-CoV-2, and spike protein, can both prime and activate the NLRP3 inflammasome in human microglia, also potentiating activation in the presence of α-synuclein, supporting a possible risk factor for COVID-19 in Parkinson’s disease and neurodegeneration." (PMID 36316366, 2023). "Purinergic receptors and NOD-like receptor protein 3 (NLRP3) inflammasome regulate inflammation and viral infection, but their effects on severe acute respiratory syndrome coronavirus 2 (SARS-CoV-2) infection remain poorly understood." (PMID 37920468, 2023). "Moreover, lung injury caused by COVID-19 has been found to activate IL-1 and NLRP3 inflammasome-mediated pathways contributing to the pathophysiology of COVID-19." (PMID 37637614, 2023). "The NLRP3 inflammasome is activated, causing CS and pyroptosis, which may operate as a COVID-19 therapeutic target and a biomarker of the severity of the disease." (PMID 36769328, 2023). "Complementary balance, especially with respect to C3 and C5 as a therapeutic approach, should be considered in the treatment of COVID-19, as they are also associated with the activation of the NLRP3 inflammasome, which generates pyroptosis, triggering tissue inflammatory aggravation." (PMID 36851766, 2023). "In addition, the tracheal NLRP3 mRNA expression in both COVID-19 variants correlated with C reactive protein (CRP) and lactate dehydrogenase (LDH) in serum as well as with the age of patients." (PMID 36498845, 2022). "Virus-infection-induced ALI/ARDS was an active area of research, and with the epidemic outbreak of COVID-19, research on the role and therapeutic potential of NLRP3 inflammasome in COVID-19-associated ALI/ARDS was emerging as a hot topic, which is still necessary to explore in the future." (PMID 36618363, 2022). "Pharmacological blockade of NLRP3 inflammasome may ameliorate underlying comorbidities associated with COVID-19, thus improving COVID-19 prognosis and attenuating the risk of death." (PMID 36263178, 2022). "Indeed SARS-CoV-2 infection promotes the activation of the NLRP3 inflammasome and is associated with COVID-19 severity." (PMID 35159254, 2022). "Inflammasome activation was also associated with COVID-19 severity and NLRP3 activation might even be a suitable predictor of COVID-19 disease severity and a potential therapeutic target." (PMID 35626754, 2022). "Due to a scarcity of patient blood samples resulting from a combination of her pregnancy and COVID-19 restrictions in hospitals, the present study primarily investigated the effects of the p.R920Q variant in circulating myeloid cells, where the NLRP3 inflammasome is predominantly expressed." (PMID 34671876, 2022). "Elevated glucose and sustained aerobic glycolysis in monocytes of COVID-19 patients are directly responsible for boosting viral replication, causing increased NLRP3 inflammasome and cytokine production, inhibition of T proliferation, and apoptosis of lung epithelial cells." (PMID 35897696, 2022). "Studies have shown that pyroptosis in COVID-19 may be associated with activation of the NLRP3 associated pyroptosis pathway." (PMID 36034662, 2022). "Studies have shown that pyroptosis in COVID-19 may be associated with activation of NLRP3, ASC, and GSDMD." (PMID 36034662, 2022). "The expression of inflammasome components (cleaved IL-1β, cleaved-CASP1, ASC, and NLRP3) was increased in COVID-19 variants and overexpressed in COVID-19/B.1.1.7 patients (p < 0.05 compared with COVID-19/B.1 variant) as indicates the immunohistochemical composite score." (PMID 36498845, 2022). "Furthermore, activation of NF-κB3 and NLRP3 inflammasome was associated with the severity of COVID-19 and poor clinical outcome." (PMID 35233748, 2022). "However, from our data it seems likely that it is ARDS and MV (stretch from MV is known to activate the inflammasome) associated with COVID-19 that drives the NLRP3 pathway." (PMID 35144622, 2022).